ENSG00000300474 (novel transcript, antisense to MTNR1A)
Gene: Long non-coding RNA gene on chromosome 4 (186,487,814 to 186,545,774, forward strand). Ensembl gene ENSG00000300474.
Gene Ontology:
Molecular function: U4 snRNA binding
Biological process: formation of quadruple SL/U4/U5/U6 snRNP; spliceosomal tri-snRNP complex assembly
Cellular component: U4/U6 x U5 tri-snRNP complex; U6 snRNP